USP19 (ubiquitin specific peptidase 19)
Diseases named in the same sentence as USP19 in open-access papers (continued):
Sharing a sentence is not in itself a finding about the gene and the disease.
gastric cancer (3 papers, 2022 to 2025). A primary or metastatic malignant neoplasm involving the stomach. "Additionally, elevated USP19 expression was observed in gastric cancer cells and tissues, and gastric cancer patients with high levels of USP19 expression had poor survival." (PMID 36646950, 2023). "On the other hand, Dong and others analyzed USP19 relevance in gastric cancer." (PMID 35646888, 2022). "Finally, using a cohort of 212 gastric cancer patients, the authors observed that USP19 expression was significantly increased in gastric cancer tissues, compared to normal gastric tissues, and the high level of USP19 expression was positively correlated with a poorer prognosis." (PMID 35646888, 2022). "USP19, which belongs to the category of potential pro-cancer factors, enhances the MMP2/MMP9 axis and related enzyme activities in patients with gastric cancer." (PMID 40280943, 2025).
Huntington disease (3 papers, 2020 to 2022). Huntington disease (HD) is a rare neurodegenerative disorder of the central nervous system characterized by unwanted choreatic movements, behavioral and psychiatric disturbances and dementia. "USP19 is also associated with polyglutamine-expanded (polyQ) diseases, including Huntington’s disease (HD) and spinocerebellar ataxia." (PMID 35897705, 2022). "USP19 is implicated in polyglutamine-expanded (polyQ) diseases, including Huntington disease (HD) and spinocerebellar ataxia." (PMID 34564439, 2021).
clear cell renal cell carcinoma (2 papers, 2023). "Interestingly, USP19-ER was shown to negatively regulate the proliferation and migration of clear cell renal cell carcinoma (ccRCC) by suppressing ERK map kinase activation." (PMID 36646950, 2023).
Epileptic encephalopathy (2 papers, 2017 to 2023). A condition in which epileptiform abnormalities are believed to contribute to the progressive disturbance in cerebral function. "She had severe neurological manifestations including epileptic encephalopathy and was previously reported with USP19 as a candidate gene." (PMID 37188825, 2023).
hepatocellular carcinoma (2 papers, 2023 to 2025). A malignant tumor that arises from hepatocytes. "For example, USP19 interacted with the WW domain of YAP and reduced the K11- and K48-linked polyubiquitination level of YAP, thus promoting hepatocellular carcinoma progression." (PMID 40962058, 2025). "Experiments using models of USP19 overexpression and knockdown demonstrated that USP19 decreased K33/K48-linked ubiquitination at the 120th lysine in SORT1 and prevented its digestion by the proteasome in hepatoma cell lines." (PMID 36834633, 2023).
lung carcinoma (2 papers, 2022 to 2023). "In our study, the opposing roles of USP19-ER and USP19-CY in TGF-β/SMAD signaling caused USP19-CY to stimulate and USP19-ER to inhibit TGF-β-induced biological processes in breast and lung cancer, including TGF-β-induced EMT and cell migration." (PMID 36646950, 2023). "In the breast and lung cancer cells that we used in our study, USP19-CY was the major isoform that was always much more highly expressed than the USP19-ER isoform." (PMID 36646950, 2023). "USP19-ER-mediated inhibition of TGF-β/SMAD signaling is causally linked to decreases in the TGF-β-induced EMT and migration of breast and lung cancer cells." (PMID 36646950, 2023). "Among members of the ZMYND family, programmed cell death 2 (PDCD2)/ZMYND7, ubiquitin specific protease 19(USP19)/ZMYND9, and beta catenin in lung cancer (BLU)/ZMYND10 only contain MYND motif in their respective carboxylterminus, with length between 30 and 40 amino acid residues." (PMID 36520265, 2022). "Notably, we showed that herboxidiene functions as a USP19 splicing modulator by strongly decreasing the mRNA expression of USP19-CY but increasing the mRNA expression of USP19-ER, as the splicing always happens at the gene level, in breast and lung cancer cells." (PMID 36646950, 2023). "In contrast, USP19-CY promotes TGF-β/SMAD-induced breast and lung cancer cell EMT, cell migration and extravasation in vitro and in vivo." (PMID 36646950, 2023).
prostate carcinoma (2 papers, 2011 to 2026). A carcinoma that arises from epithelial cells of the prostate gland. "To investigate the role of USP19 in regulating prostate cancer cell growth, we depleted this enzyme in several cell lines." (PMID 21264218, 2011). "Therefore, the USP19 modulation of prostate cancer cell growth occurs through a regulation of cell cycle progression from G0/G1 to S phase and does not affect the rate of apoptotic cell death." (PMID 21264218, 2011). "This suggests that pharmacologic inhibition of USP19 activity may be a useful novel approach for treatment of prostate cancer, including those tumors that have become unresponsive to androgen deprivation and often lead to death." (PMID 21264218, 2011). "Depletion of USP19 inhibited proliferation in prostate cancer DU145, PC-3 and 22RV1 cells, which was similar to the pattern established in fibroblasts in that it was due to decreased progression from G1 to S phase and associated with a stabilization of the cyclin-dependent kinase inhibitor p27Kip1." (PMID 21264218, 2011). "Furthermore, the prostate cancer tissue microarray revealed a positive correlation between the protein levels of ACSL4 and USP19." (PMID 41126755, 2026). "Along this line, our attempts to assess levels of USP19 in human prostate cancers by immunohistochemistry were technically not conclusive, due to low expression levels in both malignant and normal prostate tissues." (PMID 21264218, 2011). "To determine whether the reduction in the number of prostate cancer cells upon USP19 depletion resulted from a delay in cell cycle progression, we measured the cell cycle distributions of DU145 cells transfected with control or USP19 siRNAs." (PMID 21264218, 2011). "This aspect of transformation may also be present in LNCaP cells, but not in the prostate cancer cell lines that were still inhibitable by USP19 depletion." (PMID 21264218, 2011). "Therefore, the upregulation of p27Kip1 in USP19 depleted MCF10A cells appeared to be independent of KPC1, Skp2, or Pirh2 as was seen in most of the prostate cancer cell lines." (PMID 21264218, 2011).
Serous Ovarian Carcinoma (2 papers, 2021 to 2022). "A couple of recent papers presented results indicating that USP19 negatively affected proliferation and migration in clear cell renal cell and serous ovarian carcinomas." (PMID 35646888, 2022).
Autoimmunity (1 paper, 2023). The occurrence of an immune reaction against the organism's own cells or tissues. "Moreover, some of these genes, such as USP19 and RUNX1, have been implicated in autoimmunity, therefore providing a rationale for examining how their splice isoforms might regulate immune responses." (PMID 38067106, 2023).
breast invasive carcinomas (1 paper, 2019). "We found that BAP1 is highly positively correlated with RBM15B and USP19 expression in invasive breast carcinoma, UM, and colon adenocarcinoma." (PMID 30716094, 2019). "In patients with breast invasive carcinomas, BAP1 is highly positively correlated with NSG00000132153.13 (DHX30), ENSG00000259956.1 (RBM15B), and ENSG00000172046.17 (USP19), in all four categories." (PMID 30716094, 2019).
cervical cancer (1 paper, 2025). A primary or metastatic malignant neoplasm involving the cervix. "It has been found that USP19 promotes cervical cancer development by reducing the ubiquitination of Beclin-1." (PMID 40280943, 2025).
chronic heart failure (1 paper, 2024). "In the chronic heart failure model, the mRNA expression of USP19 was significantly downregulated in chronic heart failure models (Ref." (PMID 38525836, 2024).
colon adenocarcinoma (1 paper, 2019). "Importantly, USP19 and RBM15B were also among 10 genes with a high positive correlation with BAP1 expression in colon adenocarcinoma." (PMID 30716094, 2019).
fibrosis (1 paper, 2020). the formation of excess fibrous connective tissue in an organ or tissue in a reparative or reactive process. "Therefore, these lines of evidence imply that USP19 might decrease cardiac fibrosis at least via a TAK1‐p38/JNK1/2‐dependent mechanism, and the paracrine manner might participate." (PMID 32798288, 2020).
glioblastoma (1 paper, 2024). The most malignant astrocytic tumor (WHO grade IV). "USP19 is overexpressed in glioblastoma patient samples, which positively correlates with the level of MGMT protein and poor prognosis in these patients." (PMID 38644551, 2024). "Depletion of USP19 results in the glioblastoma cell sensitivity to temozolomide, which can be rescued by overexpressing MGMT." (PMID 38644551, 2024).
glioma (1 paper, 2023). A benign or malignant brain and spinal cord tumor that arises from glial cells (astrocytes, oligodendrocytes, ependymal cells). "Employing the R2 genomics platform to query the 99 DUBs for their association with the GO category of Regulation of the ERAD pathway, we identified 3 DUB genes in this category as differentially expressed in the glioma dataset: USP14, USP19, and USP25." (PMID 37892185, 2023). "This list of genes includes three DUBs (USP14, USP19, USP25) shared with the list of differentially expressed ERAD genes in glioma." (PMID 37892185, 2023).
Hyperglycemia (1 paper, 2023). An increased concentration of glucose in the blood. "USP22 in pancreatic β-cells, USP2 in adipose tissue macrophages, USP9X, 20, and 33 in myocytes, USP4, 7, 10, and 18 in hepatocytes, and USP2 in hypothalamus improve hyperglycemia, whereas USP19 in adipocytes, USP21 in myocytes, and USP2, 14, and 20 in hepatocytes promote hyperglycemia." (PMID 36834633, 2023).
Insulin resistance (1 paper, 2023). Increased resistance towards insulin, that is, diminished effectiveness of insulin in reducing blood glucose levels. "Moreover, Usp19 deficiency reduces insulin resistance in the liver and skeletal muscle." (PMID 36834633, 2023). "Since palmitate is well known to be an inducer of insulin resistance, USP19 can be considered to promote insulin resistance via adipogenesis." (PMID 36834633, 2023).
liver fibrosis (1 paper, 2021). "Recent studies identified that hedgehog signalling promoted prospero homeobox protein 1 (PROX1) expression in liver fibrosis, which inhibited HIF‐1α ubiquitination via a deubiquitinase called ubiquitin specific peptidase 19 (USP19)." (PMID 35187072, 2021).
melanoma (1 paper, 2024). A malignant, usually aggressive tumor composed of atypical, neoplastic melanocytes. "The more interesting ones, confirmed by the bibliography on melanoma, are as follows: USP15, TIPIN, TMC5, TYMP, USP19, USP8, and TFAP2B." (PMID 38928466, 2024).
myocardial ischemia (1 paper, 2021). A disorder of cardiac function caused by insufficient blood flow to the muscle tissue of the heart. "The data implied that the protective effect of C3G against I/R-induced myocardial ischemia may be relevant for USP19/Beclin1-dependent ferroptosis." (PMID 33628391, 2021).
neuroblastoma (1 paper, 2025). Neuroblastoma (NB) is the most common solid, extracranial childhood tumor. "To validate our findings in a neuron-like model, we investigated the impact of USP19-WT on TDP-43-K263E secretion in the human neuroblastoma SH-SY5Y cell line." (PMID 39948244, 2025). "We extended this work by validating USP19-mediated secretion of misfolded TDP-43 in the human SH-SY5Y neuroblastoma cell line." (PMID 39948244, 2025).
non-small cell lung carcinoma (1 paper, 2025). A group of at least three distinct histological types of lung cancer, including non-small cell squamous cell carcinoma, adenocarcinoma, and large cell carcinoma. "Unlike the indirect regulation by USP10 and the non-catalytic binding function of USP19, the classic deubiquitinating activity of USP38 makes it a potential new therapeutic target for non-small cell lung cancer (NSCLC)." (PMID 40936898, 2025).
Parkinson disease (1 paper, 2023). A progressive degenerative disorder of the central nervous system characterized by loss of dopamine producing neurons in the substantia nigra and the presence of Lewy bodies in the substantia nigra and locus coeruleus. "The USP19 deubiquitinase is found in a locus associated with Parkinson’s Disease (PD), interacts with chaperonins, and promotes secretion of α-synuclein (α-syn) through the misfolding-associated protein secretion (MAPS) pathway." (PMID 38017009, 2023). "In this report, we demonstrate a role for the USP19 deubiquitinase in mediating the progression of Parkinson’s disease pathology in a mouse model." (PMID 38017009, 2023).
primary brain tumors (1 paper, 2023). "We identified a selected group of DUBs (USP13, USP14, USP19, USP25, OTUD2/YOD1) associated with the Regulation of ERAD pathway across several adult and pediatric primary brain tumors (GBM, EPN, CPh, MB)." (PMID 37892185, 2023).
renal carcinoma (1 paper, 2022). A carcinoma arising from the epithelium of the renal parenchyma or the renal pelvis. "Hu and others utilized clear cells renal cancer (ccRCC) cell lines in vitro and demonstrated that overexpression of USP19 levels negatively affected migration and proliferation, and the opposite occurred upon USP19 silencing." (PMID 35646888, 2022).
viral infection (1 paper, 2025). "In macrophages, the deletion of USP19 following viral infection leads to an increase in TBK1 and activation of type I interferon signaling." (PMID 40083918, 2025).
cancer (19 papers, 2011 to 2026). A tumor composed of atypical neoplastic, often pleomorphic cells that invade other tissues. "The functional difference between the USP19 isoforms should be further studied in order to elucidate the molecular mechanism associated with USP19-mediated promotion of cancer pathogenesis." (PMID 34439131, 2021). "USP19 has been shown to be overexpressed in mammalian skeletal muscle in a plethora of degenerative disorders associated with muscle atrophy, including fasting and caloric restriction, diabetes, cancer, and smoking." (PMID 38716888, 2024). "Various studies have linked USP19 to different cancers, and either its overexpression or silencing may dysregulate the function of several proteins with oncogenic or tumor-suppressive properties, which in the long run may impact on the onset and development of tumors." (PMID 35646888, 2022). "Underscoring its importance in muscle physiology, the Almac Group have recently described the first-in-class inhibitor of USP19 for the treatment of cancer-induced muscle atrophy." (PMID 38716888, 2024). "In conclusion, this study showed that USP19 played a key role in TNBC cancer proliferation and apoptosis." (PMID 37700495, 2023). "Although previous studies did not specify which USP19 isoform was examined, these studies can still offer some evidence of the positive roles of USP19-CY in tumorigenesis due to its predominant expression in most cancers." (PMID 36646950, 2023). "Taken together, the findings described here implicate USP19 as a previously unrecognized target for the development of novel therapeutic alternatives for cancer treatments." (PMID 35646888, 2022). "Although further characterization is required, this observation highlights the potential of USP19 as a putative prognostic biomarker in different cancers." (PMID 35646888, 2022). "USP19 expression correlates with atrophy markers such as MuRF1 and MAFbx/atrogin‐1 in muscle biopsies of cancer patients, suggesting participation of USP19 to atrophy‐associated protein degradation." (PMID 35349763, 2022). "In particular, different lines of research indicate that USP19, a member of the DUBs, plays a role in the control of tumorigenesis and cancer dissemination." (PMID 35646888, 2022). "Taken together, USP19 appears to play a key role in tumorigenesis-related processes, such as DNA damage repair and genome instability in many human cancers, including HGSCs and ccRCC." (PMID 34439131, 2021). "Cancer recurrence occurred more frequently in the patients with lower USP19 mRNA levels and those with higher RPL23 mRNA levels." (PMID 34439131, 2021). "As expected, CORO2A was detected by immunoprecipitation using an anti-USP19 antibody, and reciprocal immunoprecipitation with an anti-CORO2A antibody also brought down USP19 in non-cancer cells (293T and 3T3-L1 cells) and cancer cells (MCF7 cells)." (PMID 27129179, 2016). "Promoting USP19-mediated deubiquitination by stabilizing DnaJC7 may offer a novel combination strategy to enhance the efficacy of cisplatin-based cancer therapy." (PMID 42193933, 2026). "Similar to NCCRP1, USP19 is aberrantly expressed in multiple cancers and may act as a tumour suppressor gene or oncogene, which relies upon the tumour type." (PMID 38106991, 2023). "In addition, Shahriyari L and collaborators described the existence of a correlation between the expression of USP19, RBM15B and the tumor suppressor gene BAP1 (BRCA1 associated protein-1) in different type of cancers." (PMID 35646888, 2022). "Since USP19 has different isoforms, and divergent effects have been observed in different cancers, it is plausible to assume that this difference could be explained by the effect these isoforms exert on differing substrates." (PMID 35646888, 2022).